FOXP3 (forkhead box P3)
Diseases named in the same sentence as FOXP3 in open-access papers (continued):
Sharing a sentence is not in itself a finding about the gene and the disease.
breast carcinoma (continued). "Several of the immune genes were expressed at a significantly lower level in the resistant than sensitive mammary tumors in the HFD offspring not treated with genistein: Foxp3 (p = 0.012), Tgfb1 (p < 0.001), Ctla4 (p = 0.023) and Il6 (p = 0.018)." (PMID 33440675, 2021). "Likewise, another study demonstrated that the number of FOXP3 and CD8 positive stromal TILs was higher in HER-2-positive breast cancer than TNBC in the invasive margin, showing similar results with this study." (PMID 32580398, 2020). "The quantities of intratumoral and stromal TIL subsets (CD8+, CD4+, and FOXP3+ TILs) in pre- and post-PST breast cancer samples, as well as changes between them, were analyzed along with their correlations with clinicopathologic features and outcome of patients." (PMID 32401825, 2020). "On comparing the number of immune cells expressing immune cell subtype-related proteins, we found that the expression of STAT6 (p = 0.005), FOXP3 (p = 0.001), CD8 (p = 0.012), CD68 (p = 0.011), and CD163 (p < 0.001) differed significantly according to the breast cancer molecular subtypes." (PMID 32580398, 2020). "In this study, we aimed to examine the effect of breast cancer cells on the expression level of ICs on CD4+ T cell subsets, including CD4+CD25−, CD4+CD25+, and CD4+CD25+FoxP3+Helios+ Tregs, in the absence and presence of anti-PD-1 mAb, anti-PD-L1 mAb or both mAbs." (PMID 31614877, 2019). "This shows that in breast cancer, CCL20 may be important in in situ recruitment or retention of FOXP3+ Tregs." (PMID 31852159, 2019). "In order to validate our findings in ex-vivo tumor tissue samples, we isolated intratumoral and peripheral pDCs from patients with breast cancer, co-cultured them with autologous peripheral CD4+CD45RA+ T cells and measured the fraction of FoxP3+ cells by flow cytometric analysis." (PMID 31440253, 2019). "In contrast, a significantly positive correlation between expression of Sdc-1 and IL-4 (r = 0.554, P = 0.032), IL-17 (r = 0.7, P = 0.004), and Foxp3 (r = 0.539, P = 0.038) was evident in breast carcinoma tissues of non-IBC." (PMID 31145753, 2019). "For example, FOXP3 binds to the promoter of miR-146a but not that of miR-146b; therefore, only miR-146a mediates FOXP3-induced apoptosis in breast cancer cells." (PMID 30700696, 2019). "In this study, neither CD8+ nor FOXP3+ TILs showed a significant relationship with prognosis in breast cancer." (PMID 30285668, 2018). "Receiver operating characteristic (ROC) analyses showed that, for advanced HER2-positive breast cancer patients, the CFR results [area under the curve (AUC): 0.708] were better than those for the other factors (AUC: CD8 = 0.681, FOXP3 = 0.639, PD1 = 0.528, PD-L1 = 0.681)." (PMID 29615076, 2018). "Studies in breast cancer have documented improved pathologic complete remission (pCR) and disease-free survival in HER2+ or triple negative breast cancer (TNBC) patients with CD8+ to Foxp3+ cell ratio (CFR) greater than 1 when assessed by immunohistochemistry." (PMID 29320521, 2018). "This suggests that although FOXP3 is usually absent in breast cancer, there are a substantial number of breast cancer samples that are positive for FOXP3." (PMID 29549328, 2018). "In the present study, we found that FOXP3 could regulate VEGF mRNA and protein levels in breast cancer cell lines." (PMID 29970908, 2018). "The percentage of CD3+CD4+CD127negCD25+FoxP3+ Treg cells were significantly higher in patients with breast cancer than in their no-known disease, age-matched counterparts." (PMID 30254632, 2018). "Foxp3 and CD44 protein levels were inversely correlated in several breast cancer cell lines." (PMID 29747682, 2018). "Small amount (1–4%) or absence of Foxp3+PD1+ cells were found in breast cancer tissues, suggesting the possibility that the phenotype of TFR cells in lymphomas and cancer does not overlap those in other physiological contexts." (PMID 29731996, 2018).
breast carcinoma (continued). "To elucidate the prognostic role of different subsets of CD4+ T cells in early breast cancer, we focus here on the CD4+ cells, forkhead box P3 (FOXP3) + CD4+ regulatory T cells (Tregs), and C-X-C motif chemokine ligand 13 (CXCL13)-positive CD4+ follicular helper T (Tfh) cells." (PMID 29482642, 2018). "Our in vitro data and in silico predictions led us to speculate that miR-155 and FOXP3 may down regulate endogenous ZEB2 in normal breast epithelia as part of epithelial homeostasis, and this is defective in breast cancer." (PMID 29963231, 2018). "Furthermore, our animal study revealed that overexpression of FOXP3 decreased serum VEGF levels, and clinical specimen analyses demonstrated that FOXP3 expression is negatively correlated with VEGF expression in breast cancer tissues." (PMID 29970908, 2018). "Therefore, by defining a mechanism for the regulation of ZEB2 independently of ZEB1, which is mediated by FOXP3 and miR-155, we have been able to analyse the specific contribution of ZEB2 in human breast cancer cells." (PMID 29963231, 2018). "The immunohistochemical results showed that VEGF levels were higher in the FOXP3-negative human primary breast cancer tissues than in the FOXP3-positive human primary breast cancer tissues." (PMID 29970908, 2018). "In cultured breast cancer cells, expression of miR-155 was induced by FOXP3 but was not significantly changed in culture medium or exosomes, suggesting that circulating miR-155 originated from blood cells." (PMID 28562349, 2017). "There is a significant body of evidence documenting the important contribution by circulating and tumour-infiltrating T effector (CD4+ and CD8+) and regulatory (FOXP3+ and CTLA-4+) cells and NK cells in immune-mediated breast cancer cell death in women with LLABCs undergoing NAC." (PMID 28913366, 2017). "Unlike normal breast epithelial cells, 60–80% of human breast cancer cells lack nuclear expression of FOXP3." (PMID 28637482, 2017). "Of note, transfection of BRCA1 shRNAs into FOXP3 Tet-off MCF7 cells reduced the induction of miR-155 by FOXP3, indicating the existence of a transcriptional mediator, BRCA1, between FOXP3 and miR-155 in human breast cancer cells." (PMID 28562349, 2017). "Likewise, as supported by our analysis of the TCGA dataset in a previous study, Pearson's analysis revealed a positive correlation (r=0.63, p<0.001) between expressions of FOXP3 and MIR155HG in primary breast cancers." (PMID 28562349, 2017). "The aim of this study was to evaluate the expression of the T cell markers CD8, FoxP3, CD3 and ζ-chain in molecular subtypes of the invasive margin and tumor center of breast cancer and corresponding sentinel nodes and to deduct prognostic information from these findings." (PMID 27473163, 2016). "Several studies revealed that FOXP3+ TILs level had a negative impact on the prognosis of breast cancer." (PMID 27566250, 2016). "Higher value of total TILs not only predicts neoadjuvant chemotherapy response, but also implies a better prognosis, whereas some subtypes of TILs, like PD-1+ TILs and Foxp3+ TILs, are not amity with breast cancer and predict an unfavorable outcome." (PMID 26459255, 2016). "The pooled HR is 1.06(95 % CI: 0.64 ~ 1.74; P > 0.05) which indicated that FOXP3+ TILs level was not correlated with RFS of breast cancers." (PMID 27566250, 2016). "In vivo analyses also validated that FOXP3-mediated induction of miR-146a resulted in the downregulation of IRAK1 and TRAF6 and subsequently inhibited NF-κB activation, thus leading to tumor suppression in breast cancer cells." (PMID 26682271, 2015). "Notably, relative to IL-17+ cells (r = 0.379; P = 0.0093), Foxp3+ cells had a more significant correlation with CD4+ TILs (r = 0.639; P = 1.4 x10−10) in breast cancer patients." (PMID 25968569, 2015). "By contrast, in breast carcinomas the degree of tumor infiltrating FoxP3+ regulatory T lymphocytes was higher in ERα-negative tumors than in ERα-positive tumors." (PMID 26318038, 2015).
breast carcinoma (continued). "Among the remaining articles whose full text was reviewed, 28 were excluded due to duplication, a lack of sufficient data, irrelevance to the prognostic value of FOXP3, or non-operable breast cancer." (PMID 26305693, 2015). "Furthermore, this review shows the new molecular targets in breast cancer: CXCR4, caveolin, miRNA, and FOXP3, as promising candidates for future development of effective and targeted therapies, also with lower toxicity." (PMID 24591761, 2014). "Of the 3,992 breast cancer patients in the original study cohort, 3,277 (82.1%) cases had intact 0.6 mm TMA cores containing infiltrating breast carcinoma and were interpretable for FOXP3 staining." (PMID 25193543, 2014). "There is a significantly increased frequency of FoxP3+, CD25+ Tregs at the lesion or tumour site in patients with HPV-induced CIN and cervical cancer as well as in other types of cancer including ovarian, lung and breast cancer." (PMID 23799135, 2013). "In agreement with previous reports, we also found that FOXP3+ infiltration is significantly increased in triple negative ductal, but not in lobular breast cancers." (PMID 22471961, 2012). "Other groups however, did not confirm these findings and only detected FOXP3 expression in breast cancer infiltrating lymphocytes." (PMID 22471961, 2012). "Similar to Foxp3 expression, SLN from breast cancer patients contained higher numbers of IDO producing cells; however, the difference between cancer and control patients was not statistically significant, and IDO expression did not predict nodal status in a regression analysis." (PMID 19604349, 2009). "We have found that FOXP3+ Tregs are abundant in tumor tissues of 56% of breast cancer patients but absent in normal tissues adjacent to the tumors." (PMID 18294387, 2008). "As observed in the HER2+ breast cancer and Kras-driven lung cancer models, MSU-42011 (~43%, p = 0.0246) and selumetinib (~43%, p = 0.0175) alone or in combination (~57%, p = 0.0016) reduced the expression of FOXP3+ in the flank tumors of MPNST compared with vehicle treatment." (PMID 40563570, 2025). "In human breast cancer (BC), CAF-S1 drives recruitment and subsequent differentiation of CD25+FOXP3+ regulatory T cells (Treg) through the engagement of surface B7H3, DPP4, and CD73 signaling." (PMID 41583489, 2025). "We first assessed the expression of ISG15 and FOXP3 in breast cancer samples using the bc‐GenExMiner database, and we found a strongly positive correlation between ISG15 and FOXP3, indicating that ISG15 might be co‐expressing with FOXP3." (PMID 38943472, 2024). "Treg cells are a subset of T cells with significant immunosuppression, characterized by the expression of Foxp3, CD25 and CD4, which are related to the disease progression and poor prognosis of multiple myeloma, lung cancer, hepatocellular carcinoma and breast cancer." (PMID 38431306, 2024). "However, to the best of our knowledge the prognostic value and the correlation between TGFβ and FoxP3 Treg cells expression in dog mammary tumors has not been investigated yet." (PMID 39165025, 2024). "TILs in breast cancer (BC) consist mainly of CD8+ cells, CD4+ cells, FOXP3+, and CD19+ cells, and less frequently CD56+ NK cells." (PMID 38672117, 2024). "For instance, in breast cancer, CD44 could induce the expression of FoxP3, which could inhibit angiogenesis by down-regulating vascular endothelial growth factor (VEGF), and FoxP3 could also induce apoptosis by controlling a miR-146/NF-κB negative feedback loop." (PMID 37569676, 2023). "However, the knockdown of the other three transcription factors (ELK1, GTF2I and FOXP3) did not reduce UBE2T expression levels in breast cancer cells." (PMID 36338541, 2022). "Thus, decreased percentage of CD4+CD25+Foxp3+ in both spleen and breast tumor tissue by naringenin and CPT might be of significant benefit for breast cancer immunotherapy." (PMID 35606804, 2022).
breast carcinoma (continued). "Furthermore, several studies recommend the evaluation of the CD8 + /FOXP3 + ratio of TILs as sensitive markers of tumor immune responses in breast cancer rather than evaluation of FOXP3 + or CD8 + TILs alone." (PMID 35438346, 2022). "Interestingly, we observed that FOXP3 was less frequently used to define Tregs in FACS studies of breast cancer, than in FACS studies of the other four types of cancer, being used in less than half the breast cancer articles." (PMID 35740658, 2022). "Similar observations were also made in other types of cancer: A large immunohistochemical study reported that high densities of FoxP3+ TIL were only indicative of improved survival in HER2+/estrogen receptor negative (ER-) breast cancer if they coincided with accumulations of CD8+ TIL." (PMID 35140715, 2022). "MSU42011, in both the MMTV-Neu model of HER2-positive breast cancer and the A/J lung cancer model, increased anti-tumor CD8 T cells, as seen by increased INFγ levels (MMTV-Neu, p = 0.0026), increased ratios of CD8:CD4, CD25 T cells, and decreased immunosuppressive FOXP3+ T cells." (PMID 34638488, 2021). "Previous findings showed that breast cancer patients with higher levels of infiltrating immune cells had more favorable prognoses, specifically with a higher ratio of tumor-infiltrating cytotoxic CD8 T cells (TILs) to immunosuppressive FoxP3+ T regulatory cells (T reg)." (PMID 34381711, 2021). "FOXP3 expression is not restricted to the lymphocyte lineage, but it is also present in some cancer cells, especially in breast cancer cells, where it has been demonstrated to be a cancer-suppressor gene and an important regulator of the HER2/ErbB2 and SKP2 oncogenes." (PMID 33671179, 2021). "Moreover, intratumoral pDCs showed the same characteristics of elevated tryptophan catabolism as well as FoxP3 induction, unlike peripheral pDCs of patients with breast cancer." (PMID 31440253, 2019). "However, to confirm that changes in Vimentin and E-cadherin expression were via direct regulation by ZEB2 and not by direct interactions with FOXP3 or miR-155, we then depleted the breast cancer cells of ZEB1 or ZEB2 using siRNAs." (PMID 29963231, 2018). "Although this is not yet known, the role of FOXP3 in breast cancer prognosis may be different for each molecular subtype of breast cancer." (PMID 30285668, 2018). "Thus, FOXP3 and miR-155 expression are high in normal human breast epithelial cells (HMEC) where ZEB2 expression is low and conversely, where ZEB2 expression is high in the human breast cancer cell lines (BT549 and MDA-MB-231), FOXP3 and miR155 expression are low." (PMID 29963231, 2018). "As FOXP3 is a transcription factor and SUMOylation has profound effects on regulating normal cell physiology, development, and tumorigenesis, we assessed the function of FOXP3 in UBC9 transcriptional activity using MCF7 human breast cancer cells in the present study." (PMID 30011797, 2018). "Since FOXP3 is a transcriptional repressor of BRCA1, a transcriptional repressor of miR-155, BRCA1 may be a mediator for transcriptional regulation of miR-155 by FOXP3 in human breast cancer cells." (PMID 28562349, 2017). "We suggest that preferential accumulation of FoxP3+Helios+ Tregs co-expressing different immune inhibitory molecules might have a negative impact on breast cancer prognosis." (PMID 28388539, 2017). "In addition, although miR-155 is unlikely to be a direct target of FOXP3 in breast cancer cells, FOXP3 directly targets and induces expression of miR-155 during development of regulatory T cells." (PMID 28562349, 2017). "This preferential accumulation of FoxP3+Helios+ Treg subset with co-expression of different immune inhibitory molecules might have a negative effect on breast cancer prognosis." (PMID 28388539, 2017). "However, recent results suggest that breast cancers may have different CD8+ CTL counts according to their ER status, which may affect the prognostic role of FOXP3." (PMID 26305693, 2015).
breast carcinoma (continued). "Together with subgroup analysis, we propose that several characteristics may have contributed to this result, such as ER- breast cancer, a non-Asian study region and the use of FOXP3-positive cut-off values other than the median." (PMID 26305693, 2015). "We could not exclude the possibility of that FOXP3 might also function as a potential transcriptional suppressor of oncogene in CRC cells as in breast cancer cells and prostate cancer." (PMID 24938080, 2014). "Similarly, almost 20% of breast cancer cells and 80% of non-malignant cells expressed nuclear FOXP3, when assessing subcellular distribution of FOXP3 in breast cancer patient samples." (PMID 24591761, 2014). "When breast cancer survival rate was correlated with location of this marker, patients with FOXP3 restricted to cytoplasm had similarly poor prognosis than patients with no detectable FOXP3." (PMID 24591761, 2014). "However, in the absence of Breg, the transformation of FoxP3+Treg was impeded and inhibited breast cancer metastasis." (PMID 23825635, 2013). "Additionally, a study on breast cancer, indicated that FAP+PDGFRβ+ CAF in tissues not only released CXCL12 to promote the migration of CD4+CD25+ T cells, but also expressed CD73, dipeptidyl peptidase IV (DPP4) and B7H3 to promote the conversion of CD4+ T cells to FOXP3+ Treg cells." (PMID 36759842, 2023). "However, when analyzed by subtype, high TILs showed a correlation with poor prognosis in TN tumors (CD8-HR 2.75, CI 0.69–10.99; FOXP3-HR 1.41, CI 0.38–5.27) and the opposite tendency in the other breast cancer subtypes, although these results were not statistically significant." (PMID 30285668, 2018). "However, interestingly, the ratio of ICOS+ CD4+ T-cells to FoxP3+ CD4+ T-cells significantly increased from 7% pre-vaccination to 23% post-vaccination, which is also accompanied by a three-fold increase in the IFN-γ response in CD4+ T-cells following vaccination to breast cancer patients." (PMID 28304339, 2017). "Notably, FOXP3 expression was not correlated with survival in ER- breast cancers, indicating that FOXP3 protein may play a different role depending on ER status." (PMID 26305693, 2015). "However, FOXP3 expression does not show a clear differential pattern in breast cancer cells and several reports have also shown that FOXP3 expression correlates with unfavorable prognosis in breast cancer." (PMID 23341929, 2013). "Briefly, HIF-1α overexpression, but not FOXP3 nor E2F1, has been reported to be closely related to high histological grade, lymph node metastasis, large tumor size, and increased angiogenesis in breast cancer, which is consistent with the function of JFK." (PMID 34336836, 2021). "Next, we examined the expression of PD-1, CTLA-4, LAG-3, TIM-3, FoxP3, and Helios in CD4+CD25− T cell subset in the presence or absence of breast cancer cells." (PMID 31614877, 2019). "Next, we investigated IC, FoxP3 and Helios expression in activated CD4+CD25+ T cells, in the presence or absence of breast cancer cells." (PMID 31614877, 2019). "In breast cancer, NAC has been well documented to significantly reduce tumour- infiltrating FOXP3+, CTLA-4+ and PD-1+ T cells (but not CD8+ T cells)." (PMID 29390966, 2018). "In HER-2 positive cancer, absolute number and percentage of circulating FOXP3+ Tregs were significantly and strikingly increased compared to HER-2 negative breast cancer and healthy donors." (PMID 24743335, 2014). "A recent study has documented enhanced FOXP3 and CTLA-4 transcripts in BMCs in breast cancer, but did not assess effect of NAC or surgery." (PMID 23320561, 2013). "Further, FOXP3 expression in inflammatory breast cancer (IBC), an aggressive subtype of breast cancer with the worst survival outcome amongst all breast cancers has not been established." (PMID 23341929, 2013).